NPAS2 (neuronal PAS domain protein 2)
Description:
Transcriptional activator which forms a core component of the circadian clock. The circadian clock, an internal time-keeping system, regulates various physiological processes through the generation of approximately 24 hour circadian rhythms in gene expression, which are translated into rhythms in metabolism and behavior. It is derived from the Latin roots 'circa' (about) and 'diem' (day) and acts as an important regulator of a wide array of physiological functions including metabolism, sleep, body temperature, blood pressure, endocrine, immune, cardiovascular, and renal function. Consists of two major components: the central clock, residing in the suprachiasmatic nucleus (SCN) of the brain, and the peripheral clocks that are present in nearly every tissue and organ system. Both the central and peripheral clocks can be reset by environmental cues, also known as Zeitgebers (German for 'timegivers'). The predominant Zeitgeber for the central clock is light, which is sensed by retina and signals directly to the SCN. The central clock entrains the peripheral clocks through neuronal and hormonal signals, body temperature and feeding-related cues, aligning all clocks with the external light/dark cycle. Circadian rhythms allow an organism to achieve temporal homeostasis with its environment at the molecular level by regulating gene expression to create a peak of protein expression once every 24 hours to control when a particular physiological process is most active with respect to the solar day. Transcription and translation of core clock components (CLOCK, NPAS2, BMAL1, BMAL2, PER1, PER2, PER3, CRY1 and CRY2) plays a critical role in rhythm generation, whereas delays imposed by post-translational modifications (PTMs) are important for determining the period (tau) of the rhythms (tau refers to the period of a rhythm and is the length, in time, of one complete cycle). A diurnal rhythm is synchronized with the day/night cycle, while the ultradian and infradian rhythms have a period shorter and longer than 24 hours, respectively. Disruptions in the circadian rhythms contribute to the pathology of cardiovascular diseases, cancer, metabolic syndromes and aging. A transcription/translation feedback loop (TTFL) forms the core of the molecular circadian clock mechanism. Transcription factors, CLOCK or NPAS2 and BMAL1 or BMAL2, form the positive limb of the feedback loop, act in the form of a heterodimer and activate the transcription of core clock genes and clock-controlled genes (involved in key metabolic processes), harboring E-box elements (5'-CACGTG-3') within their promoters. The core clock genes: PER1/2/3 and CRY1/2 which are transcriptional repressors form the negative limb of the feedback loop and interact with the CLOCK|NPAS2-BMAL1|BMAL2 heterodimer inhibiting its activity and thereby negatively regulating their own expression. This heterodimer also activates nuclear receptors NR1D1/2 and RORA/B/G, which form a second feedback loop and which activate and repress BMAL1 transcription, respectively. The NPAS2-BMAL1 heterodimer positively regulates the expression of MAOA, F7 and LDHA and modulates the circadian rhythm of daytime contrast sensitivity by regulating the rhythmic expression of adenylate cyclase type 1 (ADCY1) in the retina. NPAS2 plays an important role in sleep homeostasis and in maintaining circadian behaviors in normal light/dark and feeding conditions and in the effective synchronization of feeding behavior with scheduled food availability. Regulates the gene transcription of key metabolic pathways in the liver and is involved in DNA damage response by regulating several cell cycle and DNA repair genes. Controls the circadian rhythm of NR0B2 expression by binding rhythmically to its promoter (By similarity). Mediates the diurnal variation in the expression of GABARA1 receptor in the brain and contributes to the regulation of anxiety-like behaviors and GABAergic neurotransmission in the ventral striatum (By similarity).
Synonyms: bHLHe9; MOP4; PASD4
Tractability: No criterion of Open Targets' tractability assessment is met for any kind of drug.
Gene: Protein-coding gene on chromosome 2 (100,820,091 to 100,996,829, forward strand). Ensembl gene ENSG00000170485.
Subcellular location: Nucleus
Subcellular location (Human Protein Atlas): Nucleoplasm
Pathways (Reactome):
Circadian clock: BMAL1:CLOCK,NPAS2 activates circadian expression; Expression of BMAL (ARNTL), CLOCK, and NPAS2; Phosphorylated BMAL1:CLOCK (ARNTL:CLOCK) activates expression of core clock genes; The CRY:PER:kinase complex represses transactivation by the BMAL:CLOCK (ARNTL:CLOCK) complex
Cellular responses to stimuli: Heme signaling
Metabolism: PPARA activates gene expression
Gene Ontology:
Molecular function: DNA binding; Hsp90 protein binding; protein binding; sequence-specific double-stranded DNA binding; DNA-binding transcription factor activity; DNA-binding transcription factor activity, RNA polymerase II-specific; RNA polymerase II cis-regulatory region sequence-specific DNA binding; protein dimerization activity
Biological process: DNA damage response; positive regulation of DNA repair; positive regulation of DNA-templated transcription; response to redox state; central nervous system development; circadian regulation of gene expression; positive regulation of behavioral fear response; regulation of transcription by RNA polymerase II; response to xenobiotic stimulus; regulation of DNA-templated transcription
Cellular component: nucleus; chromatin; CLOCK-BMAL transcription complex; cytoplasm; transcription regulator complex
Genetic constraint (gnomAD): Loss-of-function variants: 19 observed, 82.37 expected, observed/expected ratio (o/e) 0.23, 90% interval 0.16 to 0.34. The upper end of that interval is the gene's LOEUF score, 0.34, which puts it in group 1 of 6, group 1 being the genes least tolerant of losing a copy. Missense variants: 664 observed, 924.95 expected, observed/expected ratio (o/e) 0.72, 90% interval 0.67 to 0.76. Synonymous variants: 351 observed, 382.41 expected, observed/expected ratio (o/e) 0.92, 90% interval 0.84 to 1.
Homologues: Orthologues: macaque NPAS2 (99% identical), chimpanzee NPAS2 (99% identical), dog NPAS2 (90% identical), mouse Npas2 (87% identical), rat Npas2 (87% identical), pig NPAS2 (86% identical), rabbit NPAS2 (84% identical), tropical clawed frog npas2 (54% identical), Drosophila melanogaster Clk (34% identical), Drosophila melanogaster tgo (14% identical), Drosophila melanogaster Met (13% identical), Drosophila melanogaster gce (13% identical), and 1 more. Paralogues in human: CLOCK (50% identical), ARNT (19% identical), ARNT2 (17% identical), BMAL1 (16% identical), BMAL2 (15% identical), PASD1 (15% identical).
Diseases named in the same sentence as NPAS2 in open-access papers:
NPAS2 is named in the same sentence as 96 diseases in open-access papers, as found by Europe PMC text mining. Sharing a sentence is not in itself a finding about the gene and the disease. The quoted sentences say what the papers report.
breast carcinoma (27 papers, 2010 to 2025). "Breast cancer risk is also associated with single nucleotide polymorphisms (SNPs) in Npas2 and Cry2, as well as Clock." (PMID 27590298, 2016). "Mutations in Npas2 seem to correlate with an increased risk of breast cancer and non-Hodgkin's lymphoma." (PMID 26288701, 2015). "Polymorphisms in Clock, Npas2 and Cry genes are often linked to increased risk or recurrence of colorectal and breast cancers, NHL, AML and endometrial ovarian cancer." (PMID 26288701, 2015). "We were not able to confirm such an association in our study; however, for another SNP, rs17024926 in the NPAS2 gene, we found a reduced risk of breast cancer in shift workers who had worked three night shifts for at least 5 yr." (PMID 23822714, 2013). "In our meta-analysis, two NPAS2 variants, rs10165970 and rs3820787, showed a statistically significant association with breast cancer in shiftworkers (<2 years of shiftwork stratification), the former with an intermediate level of evidence whereas the latter with a low level of evidence." (PMID 28177907, 2017). "Similarly, Npas2 polymorphisms are associated with increased breast cancer risk." (PMID 27590298, 2016). "As previous studies reported that NPAS2 acts as a tumour suppressor in colorectal and breast cancers." (PMID 40548841, 2025). "NPAS2 has been reported as a tumor suppressor involved in DNA damage repair in breast cancer cells; however, its role in MB remains unexplored." (PMID 40002179, 2025). "Several previous studies have reported that NPAS2 acts as a tumor suppressor in colorectal and breast cancers." (PMID 28333141, 2017). "This clock–cancer link was confirmed in later studies which showed genetic associations between some variants of the clock genes NPAS2, CRY2 and CLOCK and the risk of breast carcinoma, prostate carcinoma and Non-Hodgkin lymphoma." (PMID 28177907, 2017). "NPAS2 has also been found to be a prognostic biomarker in breast cancer, colorectal cancer and non-Hodgkin's lymphoma." (PMID 29285299, 2017). "In the subjects with three night shifts, SNPs in BMAL1 (rs2278749), BMAL2 (rs2306074), CSNK1E (rs5757037), NPAS2 (rs17024926), PER3 (rs1012477) and MTNR1A (rs131113549) were associated with decreased breast cancer risk." (PMID 23822714, 2013). "Polymorphisms in CLOCK, NPAS2, CRY2, RORA, TIMELESS, and ARNTL have been associated with breast cancer." (PMID 40534841, 2025). "Meanwhile, previous studies speculated that CDC25A was one of the direct transcriptional regulatory target genes of NPAS2, which was confirmed in breast cancer and hepatocellular carcinoma." (PMID 40548841, 2025). "The study compiled fifteen epidemiological research papers, five of which focused on shift work employment, and identified BMAL1, BMAL2, CLOCK, neuronal PAS domain protein 2 (NPAS2), CRY1, CRY2, PER1, PER3, and TIMELESS as potential risk variants for breast cancer." (PMID 39525867, 2024). "Whereas prognostic significance of the circadian gene NPAS2 in breast cancer is suggested, its application and relevance in BD requires specific testing in future studies, which, if confirmed, may serve as a predictor of prognosis." (PMID 25989161, 2015). "In addition, women in this exposure group carrying at least one variant allele of several SNPs in the other core circadian genes such as BMAL2, CSNK1E, NPAS2 and PER3 had a noteworthy reduced risk of breast cancer." (PMID 23822714, 2013). "In addition, the core clock components Clock:Bmal1, and the close homologue Npas2, have been shown to protect against chemical and radiation-induced damage, Indeed, Npas2 is being investigated as a prognostic biomarker for breast cancer." (PMID 19926479, 2010). "Variants of some circadian genes, such as neuronal PAS domain protein 2 (NPAS2), circadian locomotor output cycles kaput (CLOCK), cryptochrome circadian clock 2 (CRY2), and timeless circadian clock (TIMELESS), have been reported to be associated with breast cancer risk." (PMID 26253128, 2015).
breast carcinoma (continued). "Several of the other predictions are for proteins that have a known role in both DNA damage, NPAS2 and ID2, and breast cancer." (PMID 40646689, 2025). "Neuronal PAS domain protein 2 (NPAS2), one of the core circadian molecules, has been proved to be a potential prognostic biomarker in colorectal and breast cancers." (PMID 28333141, 2017). "In addition, putative gene interactions between NPAS2, CUL1 and RORA, CLOCK and CUL1 is observed to have correlation in the development of breast cancer." (PMID 31358835, 2019). "In vitro studies in breast cancer cell line MCF-7 by the same group, showed that KDLER1 is a transcriptional target of NPAS2, however no studies to date have demonstrated a direct malignant association." (PMID 24708840, 2014).
hepatocellular carcinoma (19 papers, 2017 to 2025). A malignant tumor that arises from hepatocytes. "NPAS2, another circadian protein, reprograms glucose metabolism in hepatocellular carcinoma (HCC) by upregulating glycolysis-related genes and downregulating PGC-1α." (PMID 39566400, 2024). "The oncogenic properties of NPAS2 have been demonstrated in various cancers like hepatocellular carcinoma and thyroid carcinoma, but the role of NPAS2 in LUAD remains unexplored." (PMID 37120564, 2023). "NPAS2 was identified as an oncogene in hepatocellular carcinoma and was related to infiltration of immune cells." (PMID 37120564, 2023). "Another study has revealed that neuronal PAS domain protein 2 promotes aerobic glycolysis of hepatocellular carcinoma cells through the transcriptional upregulation of HIF-1α, thus promoting PGC-1α downregulation." (PMID 35896535, 2022). "NPAS2 increases liver fibrosis in hepatocellular carcinoma by direct transcriptional activation of Hes1 in hepatic stellate cells and induces glucose metabolism reprogramming and cell survival by transactivating CDC25A in liver cancer cells." (PMID 35880088, 2022). "A recent study has shown that upregulated NPAS2 promoted the survival of hepatocellular carcinoma cells through the upregulation of cell division cycle 25 A (CDC25A) and inhibition of mitochondria-dependent intrinsic apoptosis." (PMID 34285836, 2021). "No core clock genes are detected among the top ten 24-h rhythmic candidate genes detected in SW620 cells, but one of the candidate genes, CDC25A, is a target of the core clock protein NPAS2 and known to promote cell survival of hepatocellular carcinoma." (PMID 32295075, 2020). "Moreover, we recently reported that overexpression of Period2 (Per2) and neuronal PAS domain protein 2 (Npas2) attenuates Zn-induced toxicity in murine hepatoma Hepa1-6 cells." (PMID 38092388, 2023). "However, to date, the potential functional roles and molecular mechanisms by which NPAS2 affects cancer cell survival are greatly unclear, especially in hepatocellular carcinoma (HCC)." (PMID 28333141, 2017). "Elevated expression of NPAS2 in hepatocellular carcinoma (HCC) triggers CDC25A transactivation, dephosphorylates Bcl-2, and ultimately inhibits apoptosis." (PMID 36978001, 2023). "Likewise, higher expression of the NPAS2 gene in tumor tissue was closely related with immune infiltration and overall survival of glioma patients as well as with immune infiltration and poor prognosis in hepatocellular carcinoma patients." (PMID 37887064, 2023). "Specifically, HIF-1α was found to be a direct transcriptional target of NPAS2, which mediates both the upregulation of glycolytic genes and the downregulation of mitochondrial biogenesis in hepatocellular carcinoma (HCC)." (PMID 33042011, 2020). "For example, Cry1 and Cry2 overexpression was associated with poor OS in gastric cancer and CRC; Npas2 was frequently upregulated in hepatocellular carcinoma (HCC) and its overexpression significantly contributed to poor prognosis of HCC patients." (PMID 32437452, 2020). "NPAS2 can be overexpressed in hepatocellular carcinoma (HCC) and induces cell survival by promoting cell proliferation and inhibiting mitochondria-related intrinsic apoptosis both in vitro and in vivo." (PMID 31139087, 2019). "In total, 563 circadian genes were differently expressed in hepatocellular carcinoma; three of them—CSNK1D, CSNK1E and NPAS2—had a high correlation with the overall survival rate in LIHC patients." (PMID 37240761, 2023).
prostate carcinoma (19 papers, 2012 to 2025). A carcinoma that arises from epithelial cells of the prostate gland. "In the finasteride group, the NPAS2 variant (rs746924) was associated with an increased associated risk of prostate cancer." (PMID 39011396, 2024). "NPAS2 variant A genes were associated with a lower risk of prostate cancer (ratio = 0.5, 95% CI, 0.3.0-1.0) in men with mild insulin resistance when compared to men with the GG genotype." (PMID 39011396, 2024). "Decreased NPAS2 expression levels were found in carriers of the T allele of rs6542993 compared with those carrying the A allele, associated with more aggressive prostate cancer and poor progression-free survival." (PMID 37887064, 2023). "Although multiple studies have found an association between NPAS2 and prostate cancer risk, few have identified a mechanism regulating this association." (PMID 38033743, 2023). "An association between NPAS2 expression and prostate cancer was also corroborated in the EPICAP study, a population-based case-control study with genotyping data that investigated the relationship between circadian gene polymorphisms and prostate cancer risk." (PMID 37887064, 2023). "The non-synonymous mutations and genetic variants rs1369481, rs895521, and rs17024926 in the NPAS2 gene were found significantly associated with susceptibility to prostate cancer, considering overall risk and risk of aggressive disease." (PMID 37887064, 2023). "NPAS2 rs6542993 was consistently associated with disease progression after adjusting for clinical confounders in two independent prostate cancer cohorts." (PMID 30996687, 2019). "We further evaluated the association of NPAS2 expression with prostate cancer outcome using the MSKCC Prostate Oncogenome Project data." (PMID 30996687, 2019). "Consistently, downregulation of NPAS2 expression was associated with more aggressive prostate cancer and poor progression-free survival (log-rank P = 0.002)." (PMID 30996687, 2019). "Consistently, the NPAS2 gene expression level was significantly lower in cases of more aggressive forms of prostate cancer (P ≤ 0.003), and a low expression level of NPAS2 was associated with poor BCR-free survival in patients with prostate cancer (P = 0.002)." (PMID 30996687, 2019). "Moreover, the circadian rhythm pathway has been associated with prostate cancer progression, where genetic variants in circadian genes such as NPAS2 have been linked to disease progression." (PMID 40046513, 2025). "Moreover, in both localized and advanced prostate cancer, SNP rs6542993 A>T of the NPAS2 gene was found significantly associated with higher risk of disease progression." (PMID 37887064, 2023). "Moreover, the A allele from NPAS2 polymorphism was associated with a reduced risk of developing prostate cancer in men with reduced IR when compared to the GG genotype carriers." (PMID 30873119, 2019). "NPAS2 has consistently emerged as one of the top genes with the greatest contribution to the observed statistical association between the circadian pathway and risk of prostate cancer in two meta-analyses of data from genome-wide association studies." (PMID 30996687, 2019). "However, the association between NPAS2 rs6542993 and prostate cancer progression was replicated across two independent and different types of cohorts, which largely reduces the chance of false-positive findings." (PMID 30996687, 2019). "The NPAS2 rs6542993 polymorphism may be a promising biomarker, and may shed light on the pathways that govern prostate cancer progression." (PMID 30996687, 2019). "The NPAS2 rs17024926 has been found to be associated with risk of prostate cancer." (PMID 23822714, 2013). "However, there are few studies on the association between NPAS2 and prostate cancer." (PMID 36978001, 2023). "PER1 and NPAS2 levels were related to all prostate cancers, while only RORA was significant for invasive tumors." (PMID 39011396, 2024).